MGMT (O-6-methylguanine-DNA methyltransferase)
Diseases named in the same sentence as MGMT in open-access papers (continued):
Sharing a sentence is not in itself a finding about the gene and the disease.
cancer (continued). "Not like direct repair involving MGMT for cancer cell survival, the role of MMR in DNA-induced apoptosis has been explored." (PMID 36575468, 2022). "We have previously reported the successful use of a non-ablative dose of ionizing radiation to prime human cancer cells to enhance the uptake of unmodified anti-MGMT morpholino oligonucleotides (AMONs) sequences to block MGMT mRNA translation." (PMID 33850305, 2022). "At the moment, it is not yet clear which and how many CpGs in the MGMT CpG island should be methylated to determine a gene silencing in cancer cells to have an impact on treatment outcome and patient survival." (PMID 35626029, 2022). "The analyzed genes in this work (SOX17, MYOD1, MAGI2, CDH1, AJAP1, MGMT, CDH13, and RASSF1A) participate in essential biological processes to maintain cell normality, and there is sufficient evidence for their protective role against the development of cancer." (PMID 34991696, 2022). "Methylation of the MGMT promoter silences this gene in cancer so that the cells no longer produce MGMT." (PMID 33442407, 2021). "Indeed, these results underscore the need for determinants beyond MGMT and MMR to predict cancer cell responsiveness to the TMZ + ATRi combination." (PMID 34676045, 2021). "In view of the considerable levels of hypermethylation in cancer cells and, for MGMT, its prognostic relevance, DAPK and MGMT show potential as epigenetic markers, in a way that additional studies may test its viability and efficacy in clinical management." (PMID 32870234, 2020). "Among cancer patients who received chemotherapy with alkylating agents, those displaying MGMT methylation had better prognosis than those without MGMT methylation." (PMID 32429269, 2020). "One advantage of promoter methylation assays is that they are generally regarded to be specific for cancer cells, since the MGMT promoter is not methylated in normal cells." (PMID 30811507, 2019). "MGMT‐expressing T98 cells are resistant to TMZ, and MGMT plays a key role in many types of cancers." (PMID 30955240, 2019). "To date, the prevalence of MGMT methylation in cancer-free individuals and its potential inheritance have not been studied." (PMID 30049288, 2018). "MGMT promoter methylation was correlated with pathological types in which it was significantly lower in serous cancer than in nonserous cancer (OR = 0.29, 95% CI = 0.14–0.59, p = .001)." (PMID 29195029, 2018). "And also, co-treatment with honokiol and O6-benzylguanine, an MGMT inhibitor, may have killed those GBM cancer stem cells." (PMID 29614990, 2018). "The coding genes affected by this epigenetic lesion cover all the molecular pathways related to cancer biology, such as DNA repair (BRCA1, MHL1 and MGMT), cell cycle (p16INK4a and p15INK4b), apoptosis (DAPK and TMS1) or cell adherence (E-cadherin and cadherin-11)." (PMID 30018746, 2018). "We report the first successful use of a non-ablative dose of ionizing radiation to prime human cancer cells to enhance the uptake of unmodified anti-MGMT morpholino oligonucleotide (AMON) sequences." (PMID 28752860, 2017). "Previously, we synthetized compounds, relying on conjugating of the MGMT inhibitors O6BG and O6BTG with a C8-linker to ß-D-glucose (the conjugates are O6BG-Glu and O6BTG-Glu respectively), in order to achieve an active targeting of cancer cells." (PMID 29066805, 2017). "In contrast, accumulation of 3H-O6BTG-Glu in VH10hTert cells was not generally lower than in cancer cells, suggesting a different uptake mechanism for glucose on one hand and glucose-conjugated MGMT inhibitors on the other." (PMID 29066805, 2017). "Many studies have demonstrated the diagnostic efficiency of DNA hypermethylation of a variety of well-known cancer-related genes, such as p16, RASSF1, APC, MGMT, DAPK, GATA5, and HOX9, in various biofluids, including bronchial aspirates, sputum, serum, plasma, and cell-free circulating DNA." (PMID 27924164, 2016).
cancer (continued). "The observation that the isopropyl moiety is a key structure that escapes recognition by MGMT can potentially be applied to cancer chemotherapy, since recent clinical trials have been undertaken to test DNA repair inhibitors that target PARP, BER, or MGMT in combination with alkylating agents." (PMID 27486975, 2016). "The result showed that the overall OR for MGMT promoter methylation in cancer cases compared with nonmalignant controls was 3.34 (95% CI = 2.34–4.76, P < 0.001)." (PMID 27824946, 2016). "TMZ sensitivity was found to be correlated with the methylation state of O6-methylguanine-DNA methyltransferase (MGMT) promoter in cancer cells committed to differentiation and not in the stem-like progenitors." (PMID 25312641, 2014). "We therefore hypothesized that the oncolytic virus-mediated RNAi of MGMT activity may enhance the antitumor effect of TMZ and provide a promising method for cancer therapy." (PMID 25295108, 2014). "GBM cancer stem cells expressing MGMT did not respond as well as non-MGMT expressing cancer stem cells at the same dosage." (PMID 25312641, 2014). "Interesting, the exposure of cancer cells to a combination of Paclitaxel and TCPOBOP increase even further, indicating that TCPOBOP potentiates MGMT gene expression, probably because TCPOBOP triplicates MGMT gene expression alone." (PMID 24959746, 2014). "It showed significantly higher frequencies of methylation of cancer-related genes (p14ARF, p15, p16INK4A, p73, TIMP3, E-cadherin, DAPK, and GSTP1) than EBV negative/ CIMP-H LLC, except for the methylation of hMLH1, and MGMT." (PMID 24188515, 2013). "Immunohistochemistry showed that MGMT expression was significantly different in the serrated lesion tissues compared with that in cancer tissues (P=0.022), control cancer tissues (P=0.002) and normal colorectal epithelial tissues (P=0.003)." (PMID 24223631, 2013). "MGMT methylation (38% vs. 28%) and MLH1 methylation (16% vs. 10%) were also more frequent in PIK3CA-mutated carcinomas compared with PIK3CA wild-type carcinomas, although neither reached statistical significance (P = 0.27 and P = 0.06, respectively)." (PMID 23785428, 2013). "We have detected aberrant methylation in five cancer-related CpGIs, that is estrogen receptor-α [ESR1 (+244bp)], O6-methylguanine-DNA methyltransferase [MGMT (-463bp)], Wilms' Tumor-1 [WT-1 (-146bp)], Breast Cancer 2 [BRCA2 (+138bp)] and Hermen Antigen [CD44 (+28bp)]." (PMID 22011321, 2011). "The promoters of ADAMTS1, MAL, and MGMT were frequently methylated in benign samples as well as in malignant tumors, independent of microsatellite instability." (PMID 19117505, 2008). "Taken together, because of higher BCRP1, MGMT and IAPs levels, CD133 positive cancer stem cells may be resistant to conventional chemotherapy and contribute to disease relapse." (PMID 17140455, 2006). "Our results may suggest that cancers with simultaneous methylation of CpG islands, so-called CpC islands methylator phenotype or CIMP+, may demonstrate the promoter methylation of both MGMT and hMLH1 genes." (PMID 12085181, 2002). "In addition to MGMT expression, TMZ resistance of CSCs in GBM is attributed to the overexpression of efflux proteins that belong to the ABC family of membrane transporters which confer stemness properties to cancer cells." (PMID 36834653, 2023). "Although 5-Aza has been reported to impact MGMT promoter in several cancers, DNA sequencing and quantification of mRNA and protein level revealed that MGMT activity was not always correlated with methylation of the core MGMT promoter." (PMID 37894860, 2023).
cancer (continued). "Overall, despite these limitations, in these large series of BTCs cases treated at three European comprehensive cancer centers and tested with three different methodologies, our results are a convincing proof of concept of the negative prognostic impact of MGMT inactivation in BTCs." (PMID 35621918, 2022). "Therefore, MGMT inhibitors do not appear to be manageable in high-dose cancer therapy with alkylating agents, unless they are locally administered, as shown in a therapeutic approach for glioblastoma." (PMID 34639014, 2021). "Interestingly, methylation of the MGMT promoter does not seem to occur uniformly in a sex-bound fashion in all cancer types." (PMID 33546098, 2021). "The DNA repair protein O6-methylguanine DNA methyltransferase (MGMT) strongly influences the effectiveness of cancer treatment with chemotherapeutic alkylating agents, and MGMT status in cancer cells could potentially contribute to tailored therapies for individual patients." (PMID 30811507, 2019). "Ex vivo treatment experiments carried out on two other MGMT promoter-methylated primary GBM cell cultures in our collection (GBM4 and GBM5) similarly detected expanded subclonal populations harboring deleterious C:G>T:A transitions in an NpCpT or NpCpC context in known cancer driver genes." (PMID 29416795, 2018). "Loss of MGMT and RRM1 was common among the four cohorts and may be predictive of response to cytotoxic therapies not currently being used to treat these cancer types." (PMID 28556593, 2017). "Therefore, we conducted a meta-analysis to assess the relationship between MGMT promoter methylation and GC by comparing cancer cases with nonmalignant controls." (PMID 27824946, 2016). "A preceding paper showed that MGMT-positive cancer cells strongly respond to the combination of temozolomide and PARP inhibitors (PARPi), whereas MGMT-deficient cells do not because MGMT-negative cells are primarily killed by unrepaired O6-methyl-guanine generated by low dose of temozolomide." (PMID 27708213, 2016). "In addition, a single exposure of cancer cells to TCPOBOP increased the expression of two tumor suppressor genes (WT1 and MGMT), which could corroborate the improved efficacy of paclitaxel in cancer cell lines." (PMID 24959746, 2014). "However, MGMT expression in cancer tissues from patients in the experimental group was not significantly different from that of the controls (P=0.500)." (PMID 24223631, 2013). "The frequencies of MGMT promote methylation ranged from 1.5% to 70.0% (median 26.1%) in NSCLC tissue and 0.0% to 55.0% (median 2.4%) in non-cancerous control, respectively, which indicated the methylation frequency in cancer tissue was much higher than that in the control group." (PMID 24086261, 2013). "Another case had negative expression of MGMT in cancer tissues and HP." (PMID 24223631, 2013). "While alkylating agents such as ifosfamide and cyclophosphamide have been applied to manage various stages of oral and other head and neck malignancy, we have not found any reports to date regarding the role of MGMT silencing in modulating response to these compounds in these cancer types." (PMID 22645611, 2012). "However, none of these cancer-selective MGMT inhibitors enters clinical trial." (PMID 38254819, 2024). "In addition, as DNA damage response has been proved to provoke the induction of chemoresistance in human cancer cells, we evaluated the association between SCD1 expression and DNA damage biomarkers, such as positive modulator MGMT and negative modulator γ-H2AX." (PMID 29354058, 2017). "Evidence from a nationwide cancer registry has suggested PPIs have a negative impact on OS for GBM patients, particularly those with MGMT promoter methylation." (PMID 39554793, 2024). "In the TCGA LGGGBM cohort there were significant differences between the patients separated by subtype (CL+ME vs. NE+PN), MGMT promoter status, 1p19q codel status, IDH status, age, grade, cancer (LGG vs. GBM), but not by gender." (PMID 32023222, 2020).
cancer (continued). "By contrast, when treating cells with melphalan, which is one of the derivatives of N-mustard for clinical use in treating cancers, the drug-induced DDR was not enhanced in MCF7 cells that had been transfected with MGMT siRNA." (PMID 26208482, 2015). "Indeed, as proof of the validity of our method, we identified many genes that are known to be differentially methylated across various cancer types (CDKN2A, CDKN2B, MGMT, SFRP1), in addition to many novel genes not previously known to be regulated by DNA methylation." (PMID 25486910, 2014).
CNS tumors (18 papers, 2018 to 2025). "MGMT (O6-Methylguanine-DNA Methyltransferase) is a well-established prognostic and diagnostic biomarker for CNS tumors." (PMID 39375809, 2024). "A comprehensive analysis of the data reveals significant implications of the TERT-p status and MGMT methylation on distinct lobes, providing valuable insights into the molecular characteristics of CNS tumors." (PMID 38893240, 2024). "Utilizing algorithms such as SVM, along with texture features extraction, offers a viable method to predict MGMT methylation status in CNS tumors." (PMID 39375809, 2024). "A meticulous examination of the data highlights the impact of the TERT-promoter status and MGMT methylation on the specific lobes, offering valuable insights into the molecular characteristics of CNS tumors." (PMID 38893240, 2024). "The intricate interplay between MGMT methylation status and prognosis underscores the critical role of epigenetics in defining the course of these aggressive CNS tumors, ultimately guiding therapeutic decisions and offering hope to both patients and clinicians." (PMID 38203783, 2024). "The design and application of new drugs to fight the CNS tumors is the need of the hour, particularly because the current therapies are restricted to hydrophobic alkylating agents, and are hindered by the expression of MGMT." (PMID 32630235, 2020). "There was missing data for IDH status and MGMT methylation status in our cohort, largely due to changing patterns of practice and the diagnosis and treatment of patients prior to the adoption of 2016 WHO CNS tumor guidelines." (PMID 39975914, 2025). "Firstly, patients were classified according to the WHO 2016 CNS tumor classification, without an assessment of IDH mutation and MGMT promoter methylation, including only patients with KPS > 60%." (PMID 40426599, 2025). "The included studies predate the latest WHO CNS tumor classification and lacked refinement in individual patient data across crucial factors such as MGMT promoter methylation, resection extent, and treatment specifics." (PMID 39593128, 2024). "Thus, both studies underscored the hypothesis that MGMT methylation can be attributed to CNS neoplasms rather than to non-neoplastic CNS diseases." (PMID 33917711, 2021).
infection (13 papers, 2018 to 2024). The state of being infected such as from the introduction of a foreign agent such as serum, vaccine, antigenic substance or organism. "U251M cells are derived from the widely used U251 cell line by infection with a lentivirus construct harboring MGMT cDNA, and consequently, these cells express high levels of exogenous MGMT." (PMID 39022643, 2024). "Thus, immune monitoring in sepsis is needed for the use of MGMT inhibitors, and down-regulated HLA-DR and lower inflammatory cytokines might be a contraindication because the overwhelming inhibition might escalate infection susceptibility." (PMID 37373287, 2023). "Nevertheless, another NSCLC cell line H520 was employed and subject to infection of Ad-MGMT, which significantly alleviated TMZ–POH’s cytotoxicity." (PMID 29426908, 2018). "TMZ–POH caused an obvious G2/M arrest in H520 cells, which was alleviated after Ad-MGMT infection, indicating TMZ–POH-induced cell cycle arrest was exacerbated by O6-BG-mediated MGMT inhibition, but alleviated by forced MGMT expression." (PMID 29426908, 2018). "Moreover, H520 was employed and subject to infection of recombinant adenoviral vector carrying the human MGMT gene (Ad-MGMT)." (PMID 29426908, 2018). "Moreover, administration of MGMT blockage should be used only in a condition with a well microbial control as inflammation is necessary for organismal control, and too less inflammation might enhance secondary infection." (PMID 37373325, 2023). "Promoter methylation is known to play an epigenetic role in TMZ chemosensitivity by suppressing O6-methylguanine-DNA methyltransferase (MGMT).Pre-clinically, it was demonstrated that DNX-2401 infection decreased the IC50 of TMZ and MGMT levels in human GBM cell lines (U87 and T98G) in vitro." (PMID 38523646, 2024). "The strains were isolated from MGMT promoter methylated (n = 4) and MGMT promoter unmethylated (n = 7) GB tumors by tissue disruption and filtration, and were subsequently grown in MRC5 cells showing a peak of viral load (1–3 log) around day 20 post-infection." (PMID 38553638, 2024). "Eleven HCMV-GBM strains were isolated from MGMT promoter methylated (n = 4) and MGMT promoter unmethylated (n = 7) GBM tumors by tissue disruption and filtration, and were subsequently grown in MRC5 cells showing a peak of viral load (1–3 log) around day 20 post-infection." (PMID 37147437, 2023).
adenocarcinoma (10 papers, 2008 to 2025). A common cancer characterized by the presence of malignant glandular cells. "ELEVATE is a single arm phase II trial testing the overall response to nivolumab following temozolomide treatment in patients with advanced unresectable previously treated adenocarcinoma which is O6-methylguanine-DNA-methyltransferase (MGMT) methylated." (PMID 36050653, 2022). "Co-localization of β-catenin and MGMT was also observed in HT-29 adenocarcinoma xenografts and in lower crypt cells of normal colon." (PMID 26603103, 2015). "Forty-two per cent of BRAF-mutated serrated adenocarcinomas showed high-level MSI (MSI-H) (P = 0.075), 100% showed hMLH1 methylation (P = 0.001) and 90.9% showed MGMT methylation (P = 0.019)." (PMID 21457162, 2011). "Their results showed two hypomethylated genes (CDKN2A and MGMT) and three hypermethylated genes (CDH13, RUNX3, APC) in adenocarcinomas compared with SCC, with the higher sensitivity and specificity values of CDH13 and APC." (PMID 32604993, 2020).
colorectal (7 papers, 2011 to 2025). "Despite these assumptions, our data suggest that an early DNA methylation event may commit the primary tumor to particular genomic trajectories, as suggested for MGMT hypermethylation preceding KRAS activating mutations in colorectal cancer." (PMID 40931149, 2025). "In the ARETHUSA trial (NCT03519412) the metastatic-colorectal patients who failed standard therapies undergo treatment with pembrolizumab, are tested for o6-methylguanine-DNA-methyltransferase (MGMT) expression (IHC), then for MGMT promoter methylation." (PMID 36230757, 2022). "We investigated the expression of MGMT in human lung by IHC in 14 specimens of normal airways and 16 lung NE cancers, including 15 SCLCs and one large cell NE lung carcinoma." (PMID 23300791, 2012).
head and neck tumors (3 papers, 2009 to 2021). "This is in agreement with the findings of Shaw and colleagues, who report MGMT percent methylation ranging from 0.0%-45% among 37 head and neck tumor samples." (PMID 19807915, 2009). "This analysis revealed that hypermethylation of CCNA1, DAPK, MGMT, SFRP1 and TIMP3 was frequent in head and neck tumor (40-70%)." (PMID 24359512, 2013). "Indirect evidence in support of our findings comes from previous reports on a negative correlation between MGMT mRNA levels and percent promoter methylation in head and neck tumors." (PMID 19807915, 2009).
degenerative disease (2 papers, 2021 to 2025). "We identified MGMT promoter hypermethylation not only in samples from patients with MS and PML, but also in those with metabolic and degenerative diseases, such as EPM, CPM and Wallerian degeneration." (PMID 33917711, 2021).